GPR15 (G protein-coupled receptor 15)
Diseases named in the same sentence as GPR15 in open-access papers (continued):
Sharing a sentence is not in itself a finding about the gene and the disease.
rheumatoid arthritis (6 papers, 2017 to 2022). A chronic, systemic autoimmune disorder characterized by inflammation in the synovial membranes and articular surfaces. "In addition, GPR15 has been linked with ulcerative colitis, rheumatoid arthritis, psoriasis, and multiple sclerosis." (PMID 30619455, 2018). "This is in line with previous human and mouse studies, which show an involvement of GPR15 in inflammatory diseases, such as inflammatory bowel disease and rheumatoid arthritis." (PMID 36613626, 2022). "For example, GPR15 expression is elevated in the peripheral blood and synovial tissue of patients with rheumatoid arthritis." (PMID 36551327, 2022). "With respect to endogenous conditions, an interesting finding was the strong upregulation of GPR15 expression at the protein level in synovial macrophages of chronically inflamed joints in the case of rheumatoid arthritis (RA)." (PMID 34639163, 2021). "GPR15 overexpression wass found in granulocytes and monocytes in joints with rheumatoid arthritis (RA) or lymphocytes in inflamed colon." (PMID 29183299, 2017). "GPR15 has been demonstrated, for instance, to be abundant on neutrophils and monocytes in the peripheral blood of rheumatoid arthritis (RA) patients as well as on macrophages and neutrophils in arthritic joints." (PMID 32922401, 2020).
ulcerative colitis (6 papers, 2018 to 2025). An inflammatory bowel disease involving the mucosal surface of the large intestine and rectum. "This also suggests the intriguing concept of increasing dietary L-Trp consumption as a non-invasive therapeutic strategy to enhance colonic GPR15+ Treg cells and prevent the onset or relapse of ulcerative colitis." (PMID 37963876, 2023). "G-protein-coupled receptor 15 (GPR15) is a known lymphocyte trafficking receptor and may serve as a pathogenic marker in inflammatory bowel disease: increased numbers of CD4+CD45RO+GPR15+ memory-type Th2 cells are found in the colon of patients with ulcerative colitis." (PMID 36016937, 2022).
enteropathy (5 papers, 2014 to 2024). "GPR15’s role in targeting lymphocytes to the gastrointestinal tract suggests the possibility that smoking may exacerbate HIV-associated enteropathy." (PMID 26441693, 2015). "In fact, this viral protein was shown to interact with Bob/GPR15, which is abundantly expressed on the basolateral surface of small intestinal epithelium, thus inducing Ca2+ signaling, microtubule loss and physiological changes resembling HIV-1-mediated enteropathy." (PMID 28661459, 2017). "In line with this, binding of HIV-1 to GPR15, an alternative co-receptor for HIV-1, has been suggested to induce enteropathy." (PMID 38500818, 2024). "Expression of GPR15 in the basal surface of the epithelium was found to coincidence with significantly increased SIV virion binding in the gut, which may induce HIV enteropathy." (PMID 35563157, 2022). "The impact of HIV-2 binding to GPR15 on enterocytes has not been investigated, but as GPR15 represent a major co-receptor for HIV-2 viruses, it is possible that direct interactions between HIV-2 and enterocytes represent one of the underlying mechanisms behind HIV-induced enteropathy." (PMID 38500818, 2024).
psoriasis (5 papers, 2018 to 2024). An autoimmune condition characterized by red, well-delineated plaques with silvery scales that are usually on the extensor surfaces and scalp. "Of particular interest are changes in the level of T cells expressing G-protein-coupled receptor 15 (GPR15), a chemokine receptor linked with multiple autoimmune diseases, including inflammatory bowel disease, multiple sclerosis and psoriasis." (PMID 32019074, 2020). "Consequently, overexpression of GPR15 is easily comprehensible in skin and intestinal inflammation conditions like psoriasis, atopic dermatitis, and lichen planus." (PMID 38790189, 2024). "Whether the interaction between GPR15L and GPR15 plays a role in the initiation of psoriasis is unknown." (PMID 36901987, 2023). "Because effects on dermal lymphocytes might potentially indirectly affect itch and inflammation by producing barrier dysfunction, some of the effects we observed in our studies may have formally arisen through GPR15 particularly in our studies using the imiquimod model of psoriasis." (PMID 35704588, 2022).
inflammatory bowel disease (4 papers, 2020 to 2022). A spectrum of small and large bowel inflammatory diseases of unknown etiology. "The role of GPR15 has also been investigated in several mouse models of inflammatory bowel disease (IBD)." (PMID 32922401, 2020).
colon cancer (3 papers, 2022 to 2024). "In mouse studies, colon cancer was induced in GPR15-deficient (KO) and GPR15-suficient (Het) mice using azoxymethane (AOM) and dextran sulfate sodium (DSS) solution in drinking water." (PMID 38074634, 2023). "To gain insights into GPR15-mediated immune function(s) in colon cancer, we assessed tumor-associated immune environment changes and the frequency of GPR15+ immune cells in the tumor compared to surgical tumor margin (STM) of human CRC samples using flow cytometry." (PMID 38074634, 2023). "Similarly, our data analysis using The Cancer Genome Atlas (TCGA) indicated that lower GPR15 expression is associated with poor survival in human colon cancer." (PMID 38074634, 2023). "Our results in the MC38 murine colon cancer model demonstrate the potential of GPR15L treatment to alleviate tumor burden in a GPR15-dependent manner." (PMID 38074634, 2023). "The experimental evidence from mouse colon cancer models and human disease strongly supports GPR15 function in immune cell infiltration of colon polyps/tumors to alter the ‘local’ immune contexture to prevent tumor development and/or mediate tumor resolution." (PMID 38074634, 2023). "Our findings in human CRC and murine AOM-DSS colon carcinogenesis model highlight a novel function of GPR15 as a tumor-suppressor by modulating the immune microenvironment in colon cancer." (PMID 38074634, 2023). "We demonstrate using human colon cancer samples that GPR15 expression and GPR15+ T cells are significantly reduced in tumors compared to surgical tumor margins (STM), which are regarded ‘tumor-free’." (PMID 38074634, 2023). "The study thus provides a glimpse of possible effects that can be mediated by GPR15 in colon cancer beyond its classical function as a T- cell trafficking protein." (PMID 38074634, 2023). "In the present study, we describe a first and novel function of GPR15 in colon cancer: GPR15 plays a crucial role in the colon recruitment of immune cells and shaping of the colon immune microenvironment to mediate a protective, tumor-mitigating effect." (PMID 38074634, 2023). "Meanwhile, one study showed that GPR15 molecules guide Treg cells into the colon tumor tissue, where they modify the tumor immune microenvironment and promote intestinal tumorigenesis." (PMID 36551327, 2022). "In the same study, integrated network analysis on GPR15 and GO enrichment analysis revealed potential intersections with proteins involved in mitogenic signaling, cell-cycle regulation and links to immune function in different cancers including colon cancer." (PMID 38074634, 2023). "GPR15 function in colon cancer is largely unexplored, motivating our current studies." (PMID 38074634, 2023). "Furthermore, it is possible that the effects of GPR15L on colon tumor growth may involve both GPR15-dependent and independent mechanisms and warrants further studies." (PMID 38074634, 2023). "In support of an anti-tumor function of GPR15 in human CRC, GPR15 expression as well as GPR15+ immune cells were significantly reduced in human colon tumors and lower GPR15 expression correlated with decreased survival of COAD patients." (PMID 38074634, 2023). "Reduced GPR15 expression on tumor-infiltrating T cells in human colon cancer and its impact on disease pathogenesis has not been previously reported and prompted us to investigate its significance using mouse colon cancer models." (PMID 38074634, 2023).
HIV enteropathy (3 papers, 2014 to 2023). A syndrome characterized by chronic, well-established diarrhea (greater than one month in duration) without an identified infectious cause after thorough evaluation, in an hiv-positive individual. "GPR15/BOB is further suggested to be involved in HIV enteropathy, a condition whereby patients with HIV infection develop malabsorption and increased intestinal permeability with diarrhoea." (PMID 24725539, 2014).
lung adenocarcinoma (3 papers, 2019 to 2021). A carcinoma that arises from the lung and is characterized by the presence of malignant glandular epithelial cells. "Additional evidence showed that the elevated expression of AHRR and GPR15 were associated with smoking-altered hypomethylations at cg14817490 and cg19859270, respectively, in lung adenocarcinoma tumor tissues." (PMID 32928150, 2020). "For lung adenocarcinoma, we found that the expression levels of three genes, GPR15, HDGF, and AHHR, were associated with increased smoking-related mutational signature, while an inverse association was observed for the other four genes, NWD1, KCNQ1, CAPN8 and RPS6KA1." (PMID 32928150, 2020). "Similarly, the biological mechanisms of how GPR15 contribute to smoking-related mutational signatures in lung adenocarcinoma remain unclear." (PMID 32928150, 2020). "Among 33 cancer types, GPR15 expression was significantly positively correlated with the prognoses of COAD, neck squamous carcinoma (HNSC), and lung adenocarcinoma (LUAD) and significantly negatively correlated with stomach adenocarcinoma (STAD)." (PMID 31835584, 2019). "In lung adenocarcinoma, our results showed that smoking increased the expression of three genes, AHRR, GPR15, and HDGF, and decreased the expression of two genes, CAPN8, and RPS6KA1, which were consequently associated with increased smoking-related mutational signature." (PMID 32928150, 2020).
lung carcinoma (3 papers, 2020 to 2025). "In addition, our results showed that the elevated expressions of AHRR and GPR15 were associated with smoking-altered hypomethylations of cg14817490 and cg19859270 in both lung cancer blood and tumor tissues, respectively." (PMID 32928150, 2020). "Higher expression is linked with some cancers (AHRR, DSC2), poorer prognosis of lung cancer (P2RY6), and cardiovascular diseases (GPR15, DCS2)." (PMID 40579423, 2025).
myocardial infarction (3 papers, 2022 to 2024). Gross necrosis of the myocardium, as a result of interruption of the blood supply to the area, as in coronary thrombosis. "In various murine heart failure models, Gpr15 expression was highly increased during the inflammatory stage of myocardial infarction and even more during acute viral myocarditis." (PMID 39195892, 2024). "In humans, we showed increased GPR15 expression after myocardial infarction, combined with altered G protein signaling pathways." (PMID 36613626, 2022). "In summary, for the first time this study showed an involvement of GPR15 in myocardial infarction, adding an important piece of the puzzle to understanding the physiological and pathophysiological role of GPR15." (PMID 36613626, 2022). "Interestingly, the associations between GPR15 mRNA expression and GPR15 DNA methylation with myocardial infarction were found to be independent of smoking status." (PMID 36613626, 2022).
Psoriasiform dermatitis (3 papers, 2021 to 2025). A skin abnormality characterized by redness and irritation, with thick, red skin that displays flaky, silver-white patches (scales). "Deficiency in Gpr15 did not alter the course of disease neither in the imiquimod-induced psoriasiform dermatitis nor in the IL-23-induced dermatitis model, despite the increased expression of C10orf99 in the inflamed skin." (PMID 37457732, 2023). "As already mentioned, deficiency in the Gpr15 gene did not alter the course of disease in imiquimod-induced psoriasiform dermatitis or the IL-23-induced dermatitis model, suggesting that C10orf99 modulates psoriasiform dermatitis via GPR15-independent pathways." (PMID 37457732, 2023). "Despite the induction of C10orf99 in psoriasiform dermatitis in mice, GPR15+ cells did not accumulate in the skin, which led to the proposal of a more GPR15-independent pathway by the author." (PMID 34639163, 2021).
colon adenocarcinoma (2 papers, 2019 to 2023). "Using large-scale publicly available data from the Cancer Genome Atlas (TCGA) and the Genotype-Tissue Expression (GTEx) databases, we found that GPR15 expression is significantly lower in colon adenocarcinoma (COAD) and rectal adenocarcinoma (READ) than in normal tissues." (PMID 31835584, 2019).
dermatitis (2 papers, 2022 to 2023). An inflammatory process affecting the skin. "It has been demonstrated that antibody-mediated skin inflammation is alleviated in GPR15-deficient mice while imiquimod-induced psoriatic dermatitis is not blunted." (PMID 35273606, 2022). "Importantly, this was associated with an increased accumulation of γδ TCR+ cells in the dermis, suggesting a possibility that GPR15 may counteract antibody-mediated skin inflammation through direct and/or indirect mechanisms that limit the recruitment of γδ TCR+ cells into the dermis." (PMID 37457732, 2023).
epidermolysis bullosa acquisita (2 papers, 2020 to 2023). "In the present study, we have addressed the role of GPR15 in the effector phase of autoantibody-mediated skin inflammation, specifically in the antibody transfer mouse model of bullous pemphigoid-like epidermolysis bullosa acquisita (BP-like EBA)." (PMID 32922401, 2020). "We therefore explored the role of GPR15 in the antibody transfer mouse model of bullous pemphigoid-like epidermolysis bullosa acquisita (BP-like EBA), a prototypical example for organ-specific, antibody-mediated autoimmunity." (PMID 32922401, 2020). "However, in the antibody transfer mouse model of bullous pemphigoid-like epidermolysis bullosa acquisita (BP-like EBA), an autoimmune subepithelial and mucocutaneous blistering disease, the Gpr15 KO was found to markedly aggravate the skin pathology." (PMID 37457732, 2023).
ischemia (2 papers, 2022 to 2023). A hypoperfusion of the BLOOD through an organ or tissue caused by a PATHOLOGIC CONSTRICTION or obstruction of its BLOOD VESSELS, or an absence of BLOOD CIRCULATION. "In addition, cardiac Gpr15 expression was significantly upregulated in a mouse model of infarction-related ischemia (>6-fold increase at five days after MI) as well as in an ischemic cardiomyocyte culture model (4-fold after 24 h induction of ischemic stress)." (PMID 37457732, 2023). "Consequently, our data imply that GPR15 might play a role in the pathogenesis of acute MI and in the conditions of ischemia, such as artery narrowing by plaques." (PMID 36613626, 2022).
lung disease (2 papers, 2017 to 2020). "As indicated, neither the proportion of GPR15+ T cells nor the methylation at cg05597521 in granulocytes differed in never-smoked patients with a lung disease compared to non-smoking volunteers." (PMID 29183299, 2017). "Regardless of the lung disease, the proportion of GPR15+ cells among lymphocyte populations as well as the degree of methylation at cg05595721 in granulocytes indicated the smoking behaviour with high specificity and sensitivity." (PMID 29183299, 2017). "However, similar to the proportion of GPR15+ T cells, the methylation at cg05597521 in granulocytes was exclusively impaired by smoking behaviour and not by lung disease in a multiple regression model." (PMID 29183299, 2017).
prostate carcinoma (2 papers, 2007 to 2019). A carcinoma that arises from epithelial cells of the prostate gland. "Further studies are required to establish any relationships between prostate cancer progression and increased expression levels of PTGDR, GPR15, and GABRE genes." (PMID 17553164, 2007).
stomach adenocarcinoma (2 papers, 2019 to 2021). "We found that the prognoses of the four cancer types, COAD, HNSC, LUAD, and stomach adenocarcinoma (STAD), are possibly (p < 0.15) associated with GPR15 expression." (PMID 31835584, 2019).
viral infection (2 papers, 2024). "GPR15 presented a decreased gene expression in shRNA E6 treatment and presented an increased level of expression in all patient groups (including NILM+) compared to control, being correlated with cervical oncogenesis and viral infection." (PMID 38790189, 2024).
Arthritis (1 paper, 2020). Inflammation of a joint. "Together, these results strongly suggest that increased arthritis development observed in mice receiving Ptpn2-haploinsufficient Tregs is due to selectively increased destabilization of GPR15+ Tregs." (PMID 33055428, 2020). "We next evaluated the number of total GPR15+ Tregs, GPR15+RORγt+FoxP3–CD4+ T cells, and GPR15+ RORγt-expressing Tregs in WT versus Ptpn2-haploinsufficient SKG mice subjected to mannan-induced arthritis." (PMID 33055428, 2020). "Despite these limitations, our study does support the idea that autoimmune-associated haploinsufficiency in Ptpn2 promotes development of arthritis through an action on a population of cTregs expressing GPR15." (PMID 33055428, 2020). "To further characterize the role of PTPN2 in the stability of resident cTregs and determine whether there is a relationship between destabilization of cTregs and enhanced arthritis in Ptpn2-haploinsufficient mice, we focused on Tregs expressing G protein–coupled receptor 15 (GPR15)." (PMID 33055428, 2020). "Overall, these results support the idea that Ptpn2 haploinsufficiency enhances DSS-induced arthritis in SKG mice by inducing a Treg-intrinsic reduction in cTreg stability, which is mainly restricted to GPR15+ cells." (PMID 33055428, 2020). "Next, we sought evidence that the selective effect of PTPN2 on the stability of GPR15+ Tregs occurs in vivo and mediates the effect of Ptpn2 haploinsufficiency on SKG arthritis." (PMID 33055428, 2020). "During mannan-induced arthritis, there were increased numbers of both GPR15+ RORγt-expressing Tregs and RORγt+FoxP3–CD4+ T cells but not of total GPR15+ Tregs in both popliteal lymph nodes and ankles of Ptpn2-haploinsufficient SKG mice." (PMID 33055428, 2020). "The marked accumulation of GPR15+ exTregs in the joints and lymph nodes of Ptpn2+/– fate-mapping mice after low-dose DSS treatment suggests that cTregs’ instability at least in part links subclinical colonic inflammation to enhanced arthritis in these mice." (PMID 33055428, 2020).
atherosclerosis (1 paper, 2022). A disease characterized by the build-up of fatty material and calcium deposition in the arterial wall resulting in partial or complete occlusion of the arterial lumen. "A possibility of evaluating the involvement of Gpr15 in the pathogenesis of MI, a combination of an atherosclerosis mouse model (e.g., apolipoprotein E knockout mice) and Gpr15 knockout mouse model might be suitable." (PMID 36613626, 2022).
autoimmune disease (1 paper, 2022). A disorder resulting from loss of function or tissue destruction of an organ or multiple organs, arising from humoral or cellular immune responses of the individual to their own tissue constituents. "Previous studies have shown that GPR15 is upregulated in immune cells in the blood and affects tissues in several autoimmune diseases." (PMID 36551327, 2022).
cataract (1 paper, 2025). Partial or complete opacity of the crystalline lens of one or both eyes that decreases visual acuity and eventually results in blindness. "Future studies should explore GPR15’s potential as both a biomarker and therapeutic target for smoking-associated cataracts." (PMID 40831670, 2025). "Given that lens oxidative stress and protein denaturation are central to cataract pathogenesis, GPR15-mediated sustained inflammatory microenvironments may accelerate lens epithelial cell damage." (PMID 40831670, 2025).